VDAC1 (voltage dependent anion channel 1)
Diseases named in the same sentence as VDAC1 in open-access papers (continued):
Sharing a sentence is not in itself a finding about the gene and the disease.
cancer (continued). "Indeed, the pivotal role of VDAC1 in regulating cancer cellular energy, metabolism, and viability is reflected in the findings that downregulation of VDAC1 expression reduced cellular ATP levels, metabolite exchange between the mitochondria and cytosol cell proliferation, and tumor growth." (PMID 34671273, 2021). "Here, we show that by altering mitochondrial function via VDAC1 silencing, we control such metabolite-induced epigenetic changes as histone acetylation and histone methylation, affecting the expression of about 2000 genes and having profound effects on cancer development." (PMID 32331482, 2020). "Thus, our study showed that VDAC1 depletion triggers reprograming of malignant cancer cells into terminally differentiated cells and that this may be a promising therapeutic approach for various cancers." (PMID 31195298, 2019). "Downregulation of VDAC1 expression in cancer may impair the exchange of metabolites between the cytosol and the mitochondria leading to inhibition of growth and proliferation of cancer cells and their ability to evade apoptosis." (PMID 31803611, 2019). "Therefore, VDAC1 is an interesting target for treating various cancers." (PMID 31803611, 2019). "Thus, our study showed that VDAC1 depletion represents a trigger for reprograming malignant cancer cells into a post-mitotic state and probably into terminally differentiated cells and that this might be a promising therapeutic approach for various cancers." (PMID 31195298, 2019). "Indeed, disrupting the VDAC1‐HK interaction is a potential strategy for cancer treatment." (PMID 29698587, 2018). "Thus, VDAC1‐based peptides offer an innovative new conceptual framework for cancer therapy." (PMID 29698587, 2018). "Thus, the increase in VDAC1 levels in cancer also contributes to this enhanced transport of Ca2+." (PMID 28443244, 2017). "Furthermore, this cluster includes genes encoding ATP5B, associated with oxidative phosphorylation (OXPHOS) and VDAC1, a gatekeeper of mitochondria, suggesting a coupling between OXPHOS and glycolysis, an important factor in cancer cell energy homeostasis (Warburg effect)." (PMID 29285267, 2017). "This review presents an overview on the multi-functional mitochondrial protein VDAC1 performing several functions and interacting with distinct sets of partners to regulate both cell life and death, and highlights the importance of the protein for cancer cell survival." (PMID 28824871, 2017). "Additional roles of this region in VDAC1 oligomerization and regulation of apoptosis are presented below (see VDAC1 Homo-Oligomer Forming the Cyto c Release Pathway) and as the binding site for HK, Bcl-2, and Bcl-xL (see VDAC1-Based Peptides As Potential Anti-Cancer Therapy)." (PMID 28824871, 2017). "Gene expression meta-analysis identified VDAC1 as a predictor of poor outcome in early stage NSCLC, and knockdown of VDAC1 expression has been shown to inhibit cancer cell proliferation and tumor growth, which prompted us to hypothesize that miR-320a may affect NSCLC cell viability through VDAC1." (PMID 27304056, 2016). "In this respect, the design of cell-penetrating VDAC1-based peptides that impair the interaction between the channel and metabolic regulators and thus impact energy homeostasis and minimize the self-defense mechanisms of cancer cells represents a novel and innovative strategy." (PMID 27289382, 2016). "Based on these results, could Vdac1 be a putative cancer driver gene in human cancer?" (PMID 26322231, 2015). "Therefore, any change in VDAC-1 expression may lead to alteration in cancer cell metabolism, ultimately promoting or inhibiting cell death." (PMID 25333947, 2014). "In summary, gene expression analysis identifies VDAC1 gene expression as a predictor of poor outcome in NSCLC and other cancers and is associated with dysregulation of a conserved set of biological pathways, which may be causally associated with aggressive tumour behaviour." (PMID 21297950, 2011).
cancer (continued). "VDAC1/PHB/MMP9‐binding compounds (SB4 and SB5) reversed activated cancer stemness markers and related signaling pathways." (PMID 41179704, 2025). "Affinity‐based proteomics revealed direct binding to voltage‐dependent anion channel 1 (VDAC1), prohibitin (PHB), and matrix metalloproteinase‐9 (MMP9), which regulate cancer stemness, motility, metabolism, and apoptosis." (PMID 41179704, 2025). "VA molecules bind to VDAC1, disrupting the NADH binding site, thereby resulting in mitochondrial dysfunction and decreased cell proliferation compared with that in non‐cancer cells." (PMID 41456957, 2025). "In vitro and in vivo studies have identified a group of VDAC antagonists (VA molecules) that selectively bind to VDAC1, demonstrating specificity for cancer cells." (PMID 41456957, 2025). "In contrast, CBX3, CHN1, SULF1 and VDAC1 were significantly elevated in SKCM compared to HD samples, while EDIL3 and PALLD demonstrated significantly lower expression levels in the cancer samples." (PMID 41350567, 2025). "Next, as cancer cell metabolism is now recognized as modifying the tumor microenvironment (TME), we evaluated the effect of reduced VDAC1 levels on the TME." (PMID 38607066, 2024). "The initiation of reprogramming malignant cancer cells into terminally differentiated cells, resulting in the reversal of their oncogenic properties within GBM, was triggered by the depletion of voltage-dependent anion channel 1 (VDAC1)." (PMID 38214842, 2024). "A marked decrease in GLUT-1, HK-I, GAPDH, and LDH, and of Kreb’s cycle and OXPHOS enzymes, supports the likelihood that cancer cells use both glycolysis and OXPHOS, suggesting that metabolism reprogramming is induced by VDAC1 silencing." (PMID 38607066, 2024). "Five core genes (ACAT1, PACS2, VDAC1, MFN1, and ATAD3A) playing critical roles in cancer were identified in this study." (PMID 36902617, 2023). "The voltage-dependent anion channel 1 (VDAC1), a pore protein located in the outer mitochondrial membrane, has been confirmed to be related to cancer in cell or animal evidence." (PMID 35958281, 2022). "VDAC1, the most abundant and best characterized VDAC isoform, has become a new pharmacologically targetable molecule for cancer therapy." (PMID 36186902, 2022). "There are three VDAC isoforms (VDAC1, VDAC2, and VDAC3), and alterations in VDAC expression have been reported already in human pathologies, including cancer." (PMID 36230654, 2022). "Voltage-dependent anion channel 1 (VDAC1), the most abundant isomers of VDAC protein family, is a key regulator in aerobic glycolysis and proliferation of cancer cell." (PMID 36703967, 2022). "In many types of cancer cells, when HK2 binds to VDAC1, the interaction between VDAC1 and Bcl-2 protein family will be blocked, resulting in a decrease in Cytc release, thus protecting tumor cells from apoptosis." (PMID 33680287, 2021). "VDAC1 and GRP75, members of a trio comprising IP3R and forming a Ca2+ ion transporting complex at MAMs are also exploited by cancer cells." (PMID 34572262, 2021). "Taking a genetic approach to targeting this protein, siRNA silencing of VDAC1 resulted in decreased MMP and ATP levels in cancer cell lines, as well as a drastic reduction of tumour burden on lung cancer xenografted mice." (PMID 31261935, 2019). "At the level of the ER and the mitochondria, expression levels of Ca2+-signaling proteins, including VDAC1, IP3R, and SERCA, are often altered in cancer cells." (PMID 29491433, 2018). "Here, cancer cell metabolism was tackled by silencing the expression of voltage-dependent anion channel 1 (VDAC1), a mitochondrial protein that controls cell energy, as well as metabolic and survival pathways and that is often over-expressed in many cancers." (PMID 30544833, 2018). "HK2 becomes overexpressed in many cancer types, either in conjunction or instead of the normal HK1 isozyme, where it binds to the outer mitochondrial membrane via the VDAC1 channel." (PMID 30400835, 2018).
cancer (continued). "The interaction of VDAC1 with HK allows for coupling between oxidative phosphorylation (OXPHOS) and glycolysis, an important factor in cancer cell energy homeostasis (i.e., the Warburg effect)." (PMID 30544833, 2018). "LC-HR-MS/MS further confirmed that expression levels of VDAC1, HK-I and SMAC were highly increased in the cancer tissues." (PMID 29285267, 2017). "VDAC1 and VDAC2 isolated after VDAC2/3 or VDAC1/3 double knockdown in cancer cells were shown to be sensitive to tubulin inhibition." (PMID 30542671, 2017). "Here, we concentrate on the interaction of VDAC1 with HK, which effectively couples OXPHOS and glycolysis, an important factor in cancer cell energy homeostasis (the Warburg effect)." (PMID 28824871, 2017). "The interaction of VDAC1 with HK mediates a coupling between OXPHOS and glycolysis (see Alterations in VDAC1 Expression Level in Cancer), while VDAC1 forms a complex with the ANT, and CrK at the contact sites between the IMM and OMM." (PMID 28824871, 2017). "VDAC1 is over-expressed in many cancer types, including GBM, where it contributes to the metabolic phenotype of cancer cells via the transport of various metabolites, nucleotides, Ca2+ and other ions across the OMM." (PMID 28412744, 2017). "However, VDAC1 is also important in mitochondria-mediated apoptosis, mediating release of apoptotic proteins and interacting with anti-apoptotic proteins, such as B-cell lymphoma 2 (Bcl-2), Bcl-xL, and hexokinase (HK), which are also highly expressed in many cancers." (PMID 28824871, 2017). "Thus, targeting these VDAC1–protein interactions may interfere with a variety of processes, such as cellular energy homeostasis, apoptosis, and other activities and signaling pathways in cancer." (PMID 28824871, 2017). "The interaction of VDAC1 with hexokinase (HK) allows for coupling between OXPHOS and glycolysis, an important factor in cancer cell energy homeostasis (the Warburg effect)." (PMID 28443244, 2017). "Specifically, voltage dependent anion channel-1 (VDAC-1), one member of the VDAC family, is thought to be a potential anti-cancer therapeutic target." (PMID 25333947, 2014). "Specifically, VDAC-1, one member of the VDAC family, was thought to be a potential anti-cancer therapeutic target." (PMID 25333947, 2014). "Collectively, our results demonstrate that structure and bioactivity‐guided synthesized new compounds intersect at the VDAC1/PHB/MMP9 crossroads and exhibit cancer‐specific cytotoxic properties, inducing apoptosis and suppressing the energy metabolism and stemness of CRC." (PMID 41179704, 2025). "Our research has shown that VDAC1, a key player in cellular metabolism, is notably overexpressed across various cancer types compared to non-cancerous tissues." (PMID 39456237, 2024). "Recently, we demonstrated that the voltage-dependent anion channel 1 (VDAC1) is highly expressed in different tumors, pointing to its significance in high energy-demanding cancer cells, and we developed several strategies targeting VDAC1 in cancers." (PMID 39272828, 2024). "Ligands typically employed for targeting tumor cells include small molecules (e.g., proteins (such as asialoglycoprotein receptor), folic acid for cancer), peptides (such as R-Tf-D-LP4, voltage-dependent anion channel 1 (VDAC1) based peptide), and nanoantibodies." (PMID 37111666, 2023). "Moreover, miR-29s induced apoptosis in cancer cells by negatively regulating anti-apoptotic proteins such as MCL-1, VDAC1/2, and CDC42/p85 complex." (PMID 36140219, 2022). "The changes in VDAC1 channel conductance and crucial protein interactions in different cancer clinical samples were not involved." (PMID 35958281, 2022). "First, this study only used bioinformatics methods to analyze the correlation between VDAC1 expression and prognosis of cancer patients in different databases, and no in vitro or in vivo validation experiments were performed." (PMID 35958281, 2022).
cancer (continued). "The VDAC1-based peptide, R-Tf-D-LP4, was tested in several cancer types and found to simultaneously attack several hallmarks of cancer, causing impairment of energy, metabolic homeostasis, inhibition of tumor growth, induction of apoptosis, and overexpression of apoptotic proteins." (PMID 36291596, 2022). "Strikingly, downregulation of VDAC1 via RNA interference was shown to limit cancer cell growth in vitro and tumor development in vivo without otherwise affecting the mice." (PMID 33477936, 2021). "VDAC1 and VDAC2 are the major ones found in mammalian cells, including cancer cells (90% of all)." (PMID 33804985, 2021). "The upregulation of VDAC1 in DAUDI cells is probably due to a compensation mechanism, which reflects the increased requirement of energy consequent to the active proliferative state of cancer cells." (PMID 34557403, 2021). "This may be due to the fact that HK2, instead of HK1, is frequently upregulated in cancer, and, in addition, the binding of HK2 to the external mitochondrial membrane in a complex with VDAC1 is known to contribute to fuel the glycolytic process." (PMID 34557403, 2021). "Finally, the reprograming of cancer cells is a process that develops over time; although VDAC1 expression was highly reduced one day after si-hVDAC1 treatment, the altered expression of proteins was seen after 15–20 days of the cells being depleted of VDAC1." (PMID 31195298, 2019). "In vitro studies demonstrated that VDA-1102 selectively detaches HK2, but not HK1, from VDAC1 leading to cancer cell apoptosis as well as glycolysis inhibition and reduction in lactate secretion, culminating in proliferation inhibition." (PMID 30400835, 2018). "We found that the expression of VDAC1 in HL-60 cells decreased after the combined treatment with ATRA (10 nM) and MEL, indicating changes in the regulation of metabolic and energetic functions of mitochondria and in the fate of cancer cells." (PMID 30248940, 2018). "To summarize, VDAC1-based peptides act relatively fast and at low concentrations to induce cell death in a variety of cancer cell lines, irrespective of the origin of the cancer or carried mutations." (PMID 28824871, 2017). "It has also been reported that VDAC3 is the most important among the three VDAC isoforms to sustain ΔΨm in cancer cells, because the high levels of free tubulin inhibit VDAC1 and VDAC2, but not VDAC3." (PMID 28713289, 2017). "In addition, some of these proteins, such as Bcl-2, Bcl-xL, and HK, are overexpressed in many cancers (see VDAC Interaction with HK and Other Metabolism-Related Proteins, Interaction of VDAC1 with Bcl-2 Family Members)." (PMID 28824871, 2017). "Nano-molar concentrations of a single siRNA specific to human VDAC1 silenced VDAC1 expression and inhibited the growth of various cancer cell types." (PMID 30542671, 2017). "Thus, although targeting cancer metabolism is challenging due to the nature of metabolic plasticity, redundancy and adaptation, VDAC1, over-expressed in GBM and a key protein in regulating cancer cell energy and metabolism, is an emerging target." (PMID 28412744, 2017). "Nevertheless, there seemed to be no significant progression in the cell cycle in these VDAC1 gene-silenced cancer cells." (PMID 26716410, 2016). "Herein, we clearly show that ATF2 can interact with VDAC1 to disrupt the HK1/VDAC complex in various cancer cells, suggesting that ATF2 might bind to VDAC1 in competing with HK1 and thus promote cytochrome c release." (PMID 25852302, 2015). "VDAC1 contributes to cancer metabolism via transport of various metabolites, mediating ATP/ADP exchange across the OMM and by the binding and channeling of mitochondrial ATP directly to HK (see Cancer Metabolism, Hexokinase and VDAC)." (PMID 23233904, 2012). "Although hexokinase II expression has been linked to worse prognosis, to date there have been no studies exploring the potential prognostic impact of VDAC1 in patients with cancer." (PMID 21297950, 2011).
cancer (continued). "It is therefore not surprising that VDAC1 has become a primary target in the fight against cancer." (PMID 37344914, 2023). "However, there has been no systematic pan-cancer focus on VDAC1 to clarify its potential clinical value in treatment and prognosis." (PMID 35958281, 2022). "The expression of VDAC1 in several cell lines was also analyzed using immunoblotting, with VDAC1-specific antibodies, showing the overexpression of VDAC1 in various cancer cell lines by up to five fold relative to VDAC1 levels in the noncancerous or transformed cells (Mef, HEK-293, and HaCat)." (PMID 35883451, 2022). "Although the exact cellular mechanisms by which CBD exerts its effects remain unclear, one potential mechanism may relate to its ability to interact with the voltage-dependent anion channel 1 (VDAC1), which is central to metabolic reprogramming, apoptosis, and a cancer drug target." (PMID 34046425, 2021). "Cancer cells express high levels of mitochondria-bound HK that not only enhances glycolysis, but also protects against mitochondria-mediated apoptosis via direct interaction with VDAC1." (PMID 34671273, 2021). "By decreasing the number of ciliated cells using colchicine, a microtubule destabilizer, or vismodegib, a Hedgehog signaling pathway inhibitor, both of which are used as anti-cancer treatments, glycolysis and respiration are clearly favored in the absence of VDAC1-ΔC." (PMID 33238609, 2020). "Similarly to the reported interactions, we find that TRAP1 interacts with CypD and VDAC1 (but not ANT) in our pan-cancer analysis." (PMID 32235444, 2020). "The role of VDAC1 in cancer has not been extensively investigated." (PMID 26322231, 2015). "The over-expression of VDAC1 in some cancer cells may be related to its multi-functional activities, as required by high energy-demanding cells (Shoshan-Barmatz and Golan, 2012; see VDAC Expression Levels in Cancers and Enhancement by Pro-apoptotic Drugs)." (PMID 23233904, 2012). "However, due to the metabolic plasticity and adaptation of cancer cells, targeting a specific, single protein may not be as effective as modulating cancer cell metabolism by depleting VDAC1, the mitochondria gate keeper." (PMID 38607066, 2024). "Therefore, depleting VDAC1 could offer a promising treatment strategy for various cancers by shifting cancer cells from a proliferative state to a non-dividing, differentiated state." (PMID 39456237, 2024). "By using D-glucose, glucose, maltose, maltotriose, and D-glucose-6-phosphate, five important carbohydrates involved in glucose metabolism, hypoxic cancer cells expressing VDAC1-ΔC, with or without VDAC1, could exhibit faster and sustained growth for a long period of energy expenditure and stress." (PMID 33238609, 2020). "However, in cancer cells, our preliminary results showed that VDAC1 is in close proximity to the centrosome (data not shown) suggesting that VDAC1 could participate in microtubule nucleation, a mechanism that we are exploring further." (PMID 33238609, 2020). "In addition, down-regulation of VDAC1 function as the mitochondrial gatekeeper, rather than attacking metabolism via targeting the metabolism of a specific enzyme, is a promising strategy to treat cancer." (PMID 30544833, 2018). "In the current study, we aimed at characterizing the expression of VDAC1 protein in OSCC, OED, and FH tissues, i.e., in cancer, a premalignant lesion, and a reactive lesion with no propensity towards transformation." (PMID 37046443, 2023). "Not coincidentally, VDAC1-HKs complexes are exploited in tumors, since mitochondrial HK2 increases the glycolysis rate, participating to the “Warburg effect,” and protects cancer cells from apoptosis." (PMID 29682501, 2018). "While not cancer, OED was never studied for VDAC1 expression before our research." (PMID 37046443, 2023).